ZNF860 (zinc finger protein 860)
Description:
May be involved in transcriptional regulation.
Tractability: PROTAC: UniProt records ubiquitination sites on it; ubiquitination databases record sites on it.
Gene: Protein-coding gene on chromosome 3 (31,981,722 to 31,991,723, forward strand). Ensembl gene ENSG00000197385.
Subcellular location: Nucleus
Subcellular location (Human Protein Atlas): Nucleoli; Nucleoli rim; Nucleoplasm
Pathways (Reactome):
Gene expression (Transcription): Generic Transcription Pathway
Gene Ontology:
Molecular function: protein binding; DNA-binding transcription factor activity, RNA polymerase II-specific; RNA polymerase II cis-regulatory region sequence-specific DNA binding
Biological process: regulation of transcription by RNA polymerase II; regulation of DNA-templated transcription
Cellular component: nucleus
Genetic constraint (gnomAD): Loss-of-function variants: 0 observed, 0.0749 expected, observed/expected ratio (o/e) 0, 90% interval 0 to 1.89. That is too few expected variants to judge how well the gene tolerates losing a copy. Missense variants: 641 observed, 776.79 expected, observed/expected ratio (o/e) 0.83, 90% interval 0.77 to 0.88. Synonymous variants: 206 observed, 257.14 expected, observed/expected ratio (o/e) 0.8, 90% interval 0.71 to 0.9.
Homologues: Orthologues: chimpanzee ZNF860 (97% identical). Paralogues in human: ZNF813 (70% identical), ZNF761 (65% identical), ZNF888 (65% identical), ZNF816 (63% identical), ZNF578 (63% identical), ZNF765 (57% identical), ZNF468 (57% identical), ZNF525 (53% identical), ZNF701 (50% identical), ZNF766 (38% identical).
Diseases named in the same sentence as ZNF860 in open-access papers:
ZNF860 is named in the same sentence as 5 diseases in open-access papers, as found by Europe PMC text mining. Sharing a sentence is not in itself a finding about the gene and the disease. The quoted sentences say what the papers report.
gastric cancer (2 papers, 2021 to 2025). A primary or metastatic malignant neoplasm involving the stomach. "ZNF860 has been associated with early-onset type 2 diabetes mellitus and prostate cancer, and its higher expression is seen as an indicator for gastric cancer." (PMID 34079582, 2021).
ZNF860 also shares sentences with these, for which no sentence is quoted: prostate carcinoma (2 papers); colorectal cancer (1); prostate tumors (1); type 2 diabetes mellitus (1).